RNASE11 (ribonuclease A family member 11 (inactive))
Synonyms: C14orf6; RAJ1; HEL-S-84p
Tractability: Antibody: UniProt places it where antibodies can reach, with high confidence; UniProt predicts a signal peptide or a membrane-spanning region; its Gene Ontology location is reachable by antibodies, with medium confidence.
Gene: Protein-coding gene on chromosome 14 (20,582,892 to 20,609,884, reverse strand). Ensembl gene ENSG00000173464.
Subcellular location: Secreted
Gene Ontology:
Molecular function: protein binding; RNA nuclease activity; nucleic acid binding
Biological process: defense response to Gram-positive bacterium
Cellular component: extracellular region
Genetic constraint (gnomAD): Loss-of-function variants: 1 observed, 2.15 expected, observed/expected ratio (o/e) 0.47, 90% interval 0.16 to 1.71. That is too few expected variants to judge how well the gene tolerates losing a copy. Missense variants: 252 observed, 251.36 expected, observed/expected ratio (o/e) 1, 90% interval 0.9 to 1.11. Synonymous variants: 105 observed, 91.19 expected, observed/expected ratio (o/e) 1.15, 90% interval 0.98 to 1.35.
Homologues: Orthologues: chimpanzee RNASE11 (98% identical), macaque RNASE11 (90% identical), guinea pig RNASE11 (64% identical), rabbit RNASE11 (63% identical). Paralogues in human: RNASE10 (21% identical), RNASE12 (17% identical), RNASE4 (16% identical), RNASE1 (15% identical), ANG (15% identical), RNASE6 (15% identical), RNASE9 (15% identical), RNASE7 (14% identical), RNASE8 (13% identical), RNASE13 (12% identical), RNASE2 (11% identical), RNASE3 (11% identical).